SETX (senataxin)
Description:
ATP-dependent 5'-3' helicase that preferentially unwinds RNA:DNA substrates over DNA:DNA substrates, playing a crucial role in resolving 5'-overhang RNA:DNA hybrids (R-loops) and promoting transcription termination. Plays a role in transcription regulation by its ability to modulate RNA Polymerase II (Pol II) binding to chromatin and through its interaction with proteins involved in transcription. Contributes to the mRNA splicing efficiency and splice site selection. Required for the resolution of R-loop RNA-DNA hybrid formation at G-rich pause sites located downstream of the poly(A) site, allowing XRN2 recruitment and XRN2-mediated degradation of the downstream cleaved RNA and hence efficient RNA polymerase II (RNAp II) transcription termination. Required for the 3' transcriptional termination of PER1 and CRY2, thus playing an important role in the circadian rhythm regulation (By similarity). Involved in DNA double-strand breaks damage response generated by oxidative stress. In association with RRP45, targets the RNA exosome complex to sites of transcription-induced DNA damage. Plays a role in the development and maturation of germ cells: essential for male meiosis, acting at the interface of transcription and meiotic recombination, and in the process of gene silencing during meiotic sex chromosome inactivation (MSCI) (By similarity). May be involved in telomeric stability through the regulation of telomere repeat-containing RNA (TERRA) transcription. Plays a role in neurite outgrowth in hippocampal cells through FGF8-activated signaling pathways. Inhibits retinoic acid-induced apoptosis.
Synonyms: ALS4; KIAA0625; SCAR1; AOA2; Sen1; STEX; SCAN2; bA479K20.2
Tractability: PROTAC: UniProt records ubiquitination sites on it; ubiquitination databases record sites on it; its protein half-life has been measured.
Gene: Protein-coding gene on chromosome 9 (132,261,356 to 132,355,048, reverse strand). Ensembl gene ENSG00000107290.
Subcellular location: Nucleus; Nucleus, nucleoplasm; Nucleus, nucleolus; Cytoplasm; Chromosome; Chromosome, telomere; Cell projection, axon; Cell projection, growth cone
Subcellular location (Human Protein Atlas): Nucleoplasm; Cytokinetic bridge
Gene Ontology:
Molecular function: 5'-3' DNA helicase activity; 5'-3' DNA/RNA helicase activity; ATP hydrolysis activity; DNA/RNA helicase activity; identical protein binding; protein binding; transcription termination site sequence-specific DNA binding; DNA binding; DNA helicase activity; helicase activity
Biological process: cellular response to hydrogen peroxide; cellular response to oxidative stress; DNA damage response; DNA-templated transcription termination; double-strand break repair; mRNA splice site recognition; positive regulation of DNA-templated transcription initiation; positive regulation of neuron projection development; positive regulation of RNA splicing; positive regulation of termination of DNA-templated transcription; positive regulation of termination of RNA polymerase II transcription, poly(A)-coupled; positive regulation of transcription by RNA polymerase II; RNA processing; termination of RNA polymerase II transcription
Cellular component: axon; chromosome; cytoplasm; growth cone; nuclear chromosome; nucleoplasm; nucleus; chromosome, telomeric region; nucleolus
Genetic constraint (gnomAD): Loss-of-function variants: 81 observed, 220.58 expected, observed/expected ratio (o/e) 0.37, 90% interval 0.31 to 0.44. The upper end of that interval is the gene's LOEUF score, 0.44, which puts it in group 1 of 6, group 1 being the genes least tolerant of losing a copy. Missense variants: 3,023 observed, 3,303.9 expected, observed/expected ratio (o/e) 0.91, 90% interval 0.89 to 0.94. Synonymous variants: 1,207 observed, 1,168.2 expected, observed/expected ratio (o/e) 1.03, 90% interval 0.99 to 1.08.
Gene-disease validity (ClinGen):
ClinGen rates the evidence that SETX causes each of these diseases.
distal hereditary motor neuropathy (autosomal dominant): Definitive.
Homologues: Orthologues: chimpanzee SETX (98% identical), macaque SETX (95% identical), dog SETX (81% identical), pig SETX (77% identical), mouse Setx (72% identical), guinea pig SETX (72% identical), rat Setx (71% identical), rabbit SETX (69% identical), tropical clawed frog setx (42% identical), zebrafish setx (30% identical), zebrafish dna2 (8% identical), Drosophila melanogaster CG6701 (7% identical), and 6 more. Paralogues in human: HELZ2 (12% identical), HELZ (8% identical), UPF1 (8% identical), IGHMBP2 (7% identical), ZNFX1 (7% identical), DNA2 (7% identical), MOV10L1 (7% identical), AQR (7% identical), MOV10 (6% identical), CT55 (1% identical).
Diseases named in the same sentence as SETX in open-access papers:
SETX is named in the same sentence as 149 diseases in open-access papers, as found by Europe PMC text mining. Sharing a sentence is not in itself a finding about the gene and the disease. The quoted sentences say what the papers report.
Ataxia (55 papers, 2006 to 2025). Ataxia refers to impaired coordination of voluntary muscle movement. "AOA2 is a recessive loss-of-function in SETX, leading to progressive cerebellar degeneration and ataxia, whereas ALS4 is caused by dominant mutations that likely confer a toxic gain-of-function or dominant-negative effect on SETX." (PMID 40332372, 2025). "A noteworthy mutation in ATM and SETX was observed among them, and its symptoms were shown to cause ataxia in these families." (PMID 39281240, 2024). "One prominent example is SETX that encodes a DNA/RNA helicase and when mutated causes a recessive form of spinocerebellar ataxia (OMIM 606002) and a dominant form of juvenile amyotrophic lateral sclerosis (OMIM 602433)." (PMID 38300321, 2024). "Senataxin (SETX) was first identified due to its association with an inherited autosomal recessive adolescent onset disorder known as ataxia with oculomotor apraxia 2 (AOA2)." (PMID 35042798, 2022). "Mutations in the DNA/RNA helicase senataxin (SETX) result in neurodegenerative disorders, ataxia with oculomotor apraxia type 2 and amyotrophic lateral sclerosis type 4 (AOA2/ALS4)." (PMID 36428700, 2022). "Senataxin (SETX) is a helicase that functions to maintain genomic stability, and SETX class‐specific mutations cause either a severe recessive ataxia (AOA2) or a dominant motor neuron disease (ALS4)." (PMID 34263556, 2021). "The senataxin (SETX) (OMIM: 608465) gene first gained attention in 2004 when a French group identified recessive mutations linked with a severe ataxia with oculo‐motor apraxia, AOA2." (PMID 34263556, 2021). "The same phenotype (disruption of the spermatogenesis characterized by an arrest of meiosis at the spermatocyte stage) was observed in ataxia with oculomotor apraxia type 2 patients who carried a mutation of the SETX gene." (PMID 34440311, 2021). "Dysfunctional TREX or RNaseH2 are linked to Aicardi-Goutières Syndrome (AGS) while SETX mutations contribute to ataxia with oculomotor apraxia (AOA2)." (PMID 31225499, 2019). "SETX variants are responsible for AR spinocerebellar ataxia (SCAR1) and AD amyotrophic lateral sclerosis (ALS4)." (PMID 30778698, 2019). "More recently, defects in the gene senataxin, which is associated with ataxia and oculomotor apraxia, was demonstrated to result in a fully dysregulated innate type 1 interferon pathway." (PMID 30385785, 2018). "The third most frequent form of ataxia in our cohort was the ataxia with oculomotor apraxia type 2 with different mutations in the SETX gene." (PMID 26068213, 2015). "In this study, we performed a mutational screening of ATM, APTX, SETX in a selected cohort of twenty-two Italian patients presenting cerebellar ataxia, sensorimotor axonal neuropathy, and elevated AFP." (PMID 23941260, 2013). "We identified the second ARCA mutation in the Cypriot population, after the FRDA GAA repeat expansion, a novel SETX homozygous c.5308_5311delGAGA mutation that co-segregates with the ataxia phenotype in a Cypriot ARCA family with 5 affected individuals." (PMID 18405395, 2008). "Polyneuropathy is present in 97.5% of patients suffering from SETX-associated ataxia and CA in 96%." (PMID 38003592, 2023). "Senataxin mutations are also associated with ataxia with oculomotor apraxia type 2 (AOA2)." (PMID 34946884, 2021). "In addition, recessive SETX mutations are reported to cause ataxia and oculomotor apraxia type 2 (AOA2)." (PMID 26843957, 2016). "Research has shown that a higher proportion of patients with early-onset cerebellar atrophy and ataxia carry variants in SNX14 (9.88%) compared to other known pathogenic genes such as GRID2 (2.47%), NPC1 (1.23%), and SETX (1.23%)." (PMID 38655056, 2024). "There are four subtypes of ataxia with oculomotor apraxia (AOA): AOA1 [mutations in APTX and/or PNKP]; AOA2 [mutations in SETX]; AOA3 [mutations in PIK3R5]; AOA4 [mutations in PNKP]." (PMID 38161589, 2023).
Ataxia (continued). "During his life, the patient underwent extensive targeted testing for known genes associated with ataxia and spasticity (spastic paraplegias 3A, 4, and 7; spinocerebellar ataxias 1, 2, 3, 6, 7, and 14; FXN‐, APTX‐, SETX‐, PLP1‐, and LCFA‐related disorders)." (PMID 34753215, 2022). "In this study, we found three genes (POLG, SETX, and PNKP) with various molecular functions, causing recessive ataxia and neuropathy." (PMID 35326432, 2022). "Senataxin (SETX) is associated with juvenile ALS in an autosomal dominant inheritance pattern and with ataxia with oculomotor apraxia type 2 in a recessive inheritance pattern." (PMID 35873773, 2022). "Further, we demonstrate that ARSACS (gene: SACS; n = 6, 22.2%), SCAR8 (gene: SYNE1; n = 5, 18.5%), SCAR9 (gene: ADCK3; n = 5, 18.5%) and AOA2 (gene: SETX; n = 4, 14.8%) are the most common recessive ataxia subtypes in the Chinese population." (PMID 34663476, 2021). "We report a mother and daughter with autosomal recessive ataxia with occulomotor apraxia in whom sequence analysis of senataxin revealed a dignosis of AOA2 (ataxia with occulomotor apraxia type 2) in both individuals." (PMID 26331048, 2015). "In our survey ~60% of juvenile-to-adult cases with cerebellar ataxia, sensorimotor neuropathy and increased AFP are due to mutations in the SETX gene, and a smaller percentage to APTX and ATM gene mutations." (PMID 23941260, 2013). "Identification of a novel truncating mutation in SETX gene in a Saudi family with AOA2 and the common reported mutation W210C in MRE11 in two families with ataxia and oculomotor apraxia supports the involvement of these genes in the disease progression." (PMID 21324166, 2011). "SETX gene is also mutated in the autosomal dominant form of juvenile amyotrophic lateral sclerosis (ALS4) and tremor/ataxia syndrome." (PMID 21324166, 2011). "The differential diagnosis in an adolescent with paroxysmal dyskinesias and ataxia includes a broad range of conditions, such as autosomal recessive cerebellar ataxias (ARCA, e.g., SETX, SYNE1 mutations), ataxia telangiectasia, organic acidemias, and juvenile-onset mitochondrial epileptic syndromes." (PMID 41568333, 2025). "The results indicate interesting mutations in SETX and ATM genes that may be the leading cause of ataxia." (PMID 39281240, 2024). "Such mutations induce an ataxia phenotype indistinguishable from those with SETX null mutation, underscoring the importance of this modification." (PMID 34263556, 2021). "Additionally, γH2AX signals were observed on apparently synapsed autosomes other than the SSC1 or SSC15, as previously observed in Ataxia with oculomotor apraxia type 2 patients or knock-out mice for the Senataxin gene." (PMID 34440311, 2021). "Coexistence with cerebellar ataxia may suggest the involvement of mutations of SOD1, ATXN2, Alsin, and SETX." (PMID 26213621, 2015). "In conclusion, we suggest that patients with ataxia, neuropathy and elevated alpha-fetoprotein should be screened for SETX and ATM genes, given that an overlapping phenotype may be present among these different genetic defined entities." (PMID 23941260, 2013). "We screened nine affected individuals from 4 families with ataxia and oculomotor apraxia for mutations in the reported genes APTX, SETX and MRE11 and identified a novel truncating mutation in SETX gene in one family and a previously reported missense mutation in MRE11 gene in two families." (PMID 21324166, 2011). "Similarly, in AOA2 or certain ataxias, providing a functional SETX helicase might reduce R-loop accumulation." (PMID 40332372, 2025). "Given the generic nature of our transcriptome findings, further studies of SETX may benefit from expanding the focus from ataxia and ALS to other types of neuro-degenerative diseases and focusing on energy restricted cellular milieu that may be characteristic to an ageing brain." (PMID 36271102, 2022).
Ataxia (continued). "Dominant mutations in SETX cause juvenile-onset amyotrophic lateral sclerosis type 4 (ALS4), while recessive mutations are associated with ataxia-oculomotor apraxia 2 (AOA2) characterized by cerebellar ataxia, oculomotor apraxia, and axonal sensorimotor neuropathy." (PMID 36553628, 2022). "Ataxia with oculomotor apraxia defines a group of genetically distinct recessive ataxias including ataxia-telangectasia (A-T, ATM gene), ataxia with oculomotor apraxia type 1 (AOA1, APTX gene) and type 2 (AOA2, SETX gene)." (PMID 23941260, 2013). "In addition, SPG11 and FUS can be sequenced in cases who also present mental retardation, while SOD1, Alsin, SETX, ATXN2 can be considered in those cases with coexistence of cerebellar ataxia." (PMID 26843957, 2016). "Lack of mutations in APTX, SETX and MRE11 genes in the third family diagnosed with ataxia and oculomotor apraxia and no cerebellar atrophy suggests the involvement of another mechanism for the development of this disorder." (PMID 21324166, 2011).
amyotrophic lateral sclerosis type 4 (26 papers, 2011 to 2025). Any amyotrophic lateral sclerosis in which the cause of the disease is a mutation in the SETX gene. "Ataxia with Oculomotor Apraxia Type 2 (AOA2) and a form of adolescent ALS (amyotrophic lateral sclerosis type 4) are caused by mutations in the Senataxin (SETX) gene, which encodes a helicase that resolves R-loops during transcription termination." (PMID 40332372, 2025). "ZPR1 is a modifier of R-loop-mediated neurodegeneration caused by alteration of senataxin function in spinal muscular atrophy and amyotrophic lateral sclerosis." (PMID 39070547, 2024). "ALS4 (Amyotrophic lateral sclerosis 4): This juvenile-onset form is an autosomal dominant distal motor neuronopathy caused by heterozygous mutations in the senataxin (SETX) gene on chromosome 9q34." (PMID 39457470, 2024). "Amyotrophic lateral sclerosis 4, caused by SETX mutation, is a unique and very interesting case of neurodegenerative disease characterized by reduced levels of R-loops." (PMID 39070547, 2024). "Mutations in SETX are linked to neurodegenerative disorders, ataxia oculomotor apraxia type 2, and amyotrophic lateral sclerosis type 4." (PMID 30419062, 2018). "The gene defective in AOA2, SETX, is also associated with amyotrophic lateral sclerosis 4 (ALS4), an autosomal dominant juvenile-onset form of ALS." (PMID 23593030, 2013). "Moreover, mutations in the SETX gene are also associated with an autosomal dominant inheritance form of the juvenile amyotrophic lateral sclerosis 4 (ALS4) (OMIM 602433)." (PMID 36438189, 2022). "Notably, SETX is ubiquitously expressed in various cell types, and genetic mutations of it are found in patients with amyotrophic lateral sclerosis 4 (ALS4) and ataxia-oculomotor apraxia (AOA2)." (PMID 36135313, 2022). "Human senataxin, the mammalian Sen1 homolog, was initially identified when mutations causing ataxia oculomotor apraxia 2 (AOA2) and amyotrophic lateral sclerosis type 4 (ALS4) were mapped to the senataxin gene (SETX) (reviewed in James and Talbot, 2006; Palau and Espinós, 2006)." (PMID 21700224, 2011). "In a similar study, our group used WGCNA to identify transcriptomic networks from peripheral blood of controls and ALS4 (Amyotrophic Lateral Sclerosis Type 4) patients, a motor neuron disorder also caused by mutations in the SETX gene." (PMID 40413398, 2025). "Mutations in the RNA:DNA helicase senataxin (SETX) mutations are implicated in the dominant juvenile form of amyotrophic lateral sclerosis type 4 (ALS4) and a recessive form of ataxia oculomotor apraxia type 2 (AOA2)." (PMID 26579211, 2015). "Senataxin (SETX) is an RNA:DNA helicase mutated in Axonal neuropathy type 2 (AOA2) and Amyotrophic Lateral Sclerosis type 4 (ALS4) patients, with functions at the interface between transcription and genome maintenance pathways." (PMID 36543851, 2022). "The R-loop resolving SETX helicase is associated with neurological disorders like AOA2 (ataxia with oculomotor apraxia type 2) and ALS4 (amyotrophic lateral sclerosis 4)." (PMID 33505970, 2020). "The SETX gene, for example, has been implicated in the pathogenesis of two distinct neurological conditions, namely ataxia with oculomotor apraxia type 2 (AOA2) and amyotrophic lateral sclerosis type 4 (ALS4)." (PMID 40725463, 2025). "Also, in patients with amyotrophic lateral sclerosis 4 (ALS4), caused by mutations in senataxin, R-loops have been shown to block DNA methylation at gene promoters and inhibit DNA methyl-transferase-1 (DNMT1) activity leading to activation of the TGFb pathway." (PMID 39342995, 2024). "Pathogenic variants in SETX cause two distinct neurological diseases, a loss-of-function recessive disorder, ataxia with oculomotor apraxia type 2 (AOA2), and a dominant gain-of-function motor neuron disorder, amyotrophic lateral sclerosis type 4 (ALS4)." (PMID 34922620, 2021).
amyotrophic lateral sclerosis type 4 (continued). "Senataxin is a large 303 kDa protein linked to neuron survival, as recessive mutations cause Ataxia with Oculomotor Apraxia type 2 (AOA2), and dominant mutations cause amyotrophic lateral sclerosis type 4 (ALS4)." (PMID 24244371, 2013). "SETX mutations underlie two inherited neurodegenerative diseases: Ataxia with Oculomotor Apraxia type 2 (AOA2) and Amyotrophic Lateral Sclerosis type 4 (ALS4)." (PMID 34263556, 2021). "The role of SETX is seen in two juvenile-onset neurodegenerative disorders: Ataxia with Oculomotor Apraxia type 2 (AOA2) and Amyotrophic Lateral Sclerosis type 4 (ALS4)." (PMID 34445553, 2021).